SKP2 (S-phase kinase associated protein 2)
Diseases named in the same sentence as SKP2 in open-access papers (continued):
Sharing a sentence is not in itself a finding about the gene and the disease.
colon carcinoma (13 papers, 2015 to 2025). "SKP2 is a critical regulator of cell cycle progression and is frequently overexpressed in various cancers, including colon cancers." (PMID 40004973, 2025). "This methylation enhances the interaction of FOXO1 with S-phase kinase-associated protein 2 (SKP2), an E3 ubiquitin ligase, resulting in the degradation of FOXO1 and increasing colon cancer cell proliferation." (PMID 35740522, 2022). "The SKP2 protein is oncogenic and overexpressed in several human malignancies, such as breast and colon cancers." (PMID 35313079, 2022). "TCGA gene profile of Skp2 in tumors indicates the relative low amplification in ovary and colon tumors." (PMID 30086790, 2018). "The Cancer Genome Atlas (TCGA) data also showed the very rare amplification of Skp2 in both ovary and colon cancers." (PMID 30086790, 2018). "Knockdown of Skp2 also attenuates the migration of colon carcinoma and gastric cancer cells." (PMID 37089937, 2023). "However, to our surprise, treatment with AUY922 only moderately reduced the expression of mutant BRAF while it abolished the expression of other HSP90 client proteins such as CRAF and SKP2 in mutant BRAF colon cancer cells." (PMID 27391062, 2016). "Moreover, SKP2 promotes the maintenance of an undifferentiated state in normal and in colon cancer cells." (PMID 38102140, 2023). "Notably, SKP2 expression was found to be significantly up-regulated in colon cancers in comparison with non-malignant adjacent colon tissues and its expression level was inversely correlated with AES expression, as demonstrated by bioinformatics analysis of TCGA database." (PMID 33754069, 2021). "Similarly, we observed there was no evident Skp2 protein level change in our analyzed colon tumor samples either, hinting there are a subset of tumors with low p27 and Skp2 expressions, which also indicating the p27 downregulation is not resulted from high Skp2-mediated degradation." (PMID 30086790, 2018).
multiple myeloma (12 papers, 2006 to 2024). "Interestingly, recent studies show that hnRNPU-derived hsa_circ_0017272 is able to encode a protein consisting of 603 aa, which promotes the proliferation of multiple myeloma cells via regulating exon skipping of S-phase kinase associated protein 2 and stabilizing c-Myc protein." (PMID 37993881, 2023). "Results from TCGA depict that leukemia showed a marginally increased trend in Skp2 expression compared to leukemia and myeloma." (PMID 38559562, 2024). "DT204 is an Skp2 inhibitor identified by virtual and computational screening against multiple myeloma RPMI8226 cells." (PMID 37089937, 2023). "The knockdown of Skp2 expression sensitized BTZ-resistant multiple myeloma cells to proteasome inhibitors." (PMID 37089937, 2023). "Moreover, individual components of the SCF complex, including Cullin1, S-phase kinase associated protein 2 (Skp2), copper metabolism domain containing 1 (Commd1), and cyclin-dependent kinases regulatory subunit 1(Cks1b) have been linked to Bortezomib resistance in multiple myeloma." (PMID 30885218, 2019). "CKS1B has been shown overexpression in aggressive disease and regulated multiple myeloma growth and survival through SKP2- and p27Kip1-dependent and -independent mechanisms." (PMID 27270326, 2016). "Our findings explain why SKP2 knockdown or p27Kip1 over-expression induces less myeloma cell growth inhibition and cell death than CKS1B knockdown." (PMID 20930946, 2010). "In multiple myeloma, for example, inhibition of the PI3K/Akt pathway by LY294002 resulted in p27 accumulation, which, in turn, was associated with a decrease in Skp2 levels." (PMID 16859513, 2006). "In addition, SKP2 inhibitor DT204 enhances the efficacy of BTZ-based therapies in multiple myeloma patients who are already BTZ-resistant." (PMID 38559562, 2024). "Furthermore, inhibition of Skp2 has been shown to overcome the resistance to Bortezomib in multiple myeloma." (PMID 30885218, 2019). "Thus, our findings clarify the SKP2/ p27Kip1-independent mechanisms of CKS1B activity in maintaining myeloma cell growth and survival, and also provide a rationale for specifically targeting STAT3 and MEK/ERK/BCL2 in aggressive CKS1B-overexpressing MM." (PMID 20930946, 2010). "However, the mechanisms that down-regulate Skp2 expression by inhibition of this pathway in multiple myeloma or in any other cancer are at present unknown." (PMID 16859513, 2006). "Recent studies denote combining a novel SKP2 inhibitor DT204 and BTZ synergistically induced anti-myeloma activity and sensitized drug resistance in MM." (PMID 38559562, 2024). "Another SKP2 antagonist of this type is DT204, which overcomes Bortezomib resistance in multiple myeloma by reducing the interaction of SKP2 with Cullin1 and Commd1 adaptor thereby disrupting SCFSKP2 complex." (PMID 36881608, 2023). "Another example, the SCFSkp2 components related to BTZ resistance, and combined use of BTZ and Skp2 inhibitor inhibits BTZ-resistant multiple myeloma growth, rendering targeting SCFSkp2as a strategy to overcome therapeutic resistance in multiple myeloma." (PMID 37089937, 2023). "Here we demonstrate the crucial role of CKS1B in multiple myeloma (MM) progression and define CKS1B-mediated SKP2/p27Kip1-independent down-stream signaling pathways." (PMID 20930946, 2010). "The aim of the present study was to further clarify the functional role of CKS1B in myeloma cell survival and drug-resistance by investigating CKS1B-induced SKP2- and p27Kip1-independent signaling pathways." (PMID 20930946, 2010).
nasopharyngeal carcinoma (12 papers, 2012 to 2025). A carcinoma arising from the nasopharyngeal epithelium. "Furthermore, the upregulation of PC2, via activation of the Skp2/c-Myc pathway, has been associated with higher T stage and worse patient survival with nasopharyngeal carcinoma." (PMID 40299470, 2025). "Several statistical analyses showed that SKP2 promotes the progression and induces tumorigenesis of nasopharyngeal carcinoma and accelerates the growth of renal cell carcinoma." (PMID 34869393, 2021). "Depletion of Skp2 sensitized cells to cisplatin treatment, highlighting a promising approach for Skp2 targeting therapy in nasopharyngeal carcinoma (NPC) treatment." (PMID 34068643, 2021).
retinoblastoma (12 papers, 2015 to 2025). A malignant tumor that originates in the nuclear layer of the retina. "RB1-deficient human retinoblastoma cells undergo apoptosis after Skp2 knockdown via the activation of p27." (PMID 33591981, 2021). "RB1-deficient human retinoblastoma cells underwent apoptosis after Skp2 knockdown and small molecule inhibitors of SKP2 were SL in RB1 defective triple negative breast tumor cells." (PMID 33591981, 2021). "Likewise, the S-phase associated kinase 2 (SKP2) regulate cell cycle entry and is required for cone precursor and retinoblastoma cell proliferation." (PMID 28445155, 2017). "Recognizing that SKP2 loss causes synthetic lethality in RB1 null cells, Aubry and colleagues explored the therapeutic potential of the SKP2 inhibitor MLN4924 in treating retinoblastoma." (PMID 38672640, 2024). "SKP2 directly interacts with Rb and has previously been shown to be required for the hyper-proliferative phenotype of Rb-depleted human retinoblastoma cells, via its regulatory control over p27 levels." (PMID 29915391, 2018). "CDK2 being a protein known to cause tumour penetrance in all retinoblastoma models, removal of p107 in an Rb knockout model causing activation of CDK2 and post transcriptional induction of S-phase kinase-associated protein 2 (SKP2) further established the crosstalk among these proteins." (PMID 37667345, 2023). "The overexpression of Skp2 in retinoblastoma can restore suppressed retinoblastoma growth." (PMID 35845132, 2022). "Thus, intravitreal MLN4924 is a promising new retinoblastoma therapy, mimicking the cancer-specific lethality of eliminating SKP2 complexes." (PMID 32123578, 2020). "Whether SKP2 is synthetic lethal in MYCNamp retinoblastoma is unclear." (PMID 32123578, 2020). "We compared the relative levels of expression of SKP2, p27, pRb, and ppRb proteins in four MYCN‐amplified and one MYCN‐low retinoblastomas by immunohistochemistry (IHC) staining of tumor sections with antibodies specific for these proteins." (PMID 28211617, 2017).
chronic myeloid leukemia (11 papers, 2016 to 2024). "For example, inhibition of Skp2 expression can sensitize chronic myeloid leukemia cells to imatinib and induce cell apoptosis." (PMID 35845132, 2022). "USP10 deubiquitinates SKP2 and augments the activation of Bcr-Abl by mediating deubiquitination and stabilization of SKP2 in chronic myelogenous leukemia cells." (PMID 32268558, 2020). "Our previous study showed that Spautin-1 inhibits the growth of chronic myeloid leukemia via promoting the degradation of the oncoprotein, SKP2." (PMID 30975171, 2019). "In chronic myeloid leukemia cells, USP10 amplified the activation of Bcr-Abl by mediating the deubiquitination of SKP2 and stabilization." (PMID 37915040, 2023). "Although bortezomib is not a specific inhibitor of Skp2, it protected p27 from Skp2-mediated ubiquitination by inhibiting the proteasome function, resulting in suppressed colony formation ability of chronic myelogenous leukemia cells and increased apoptosis rate." (PMID 31038581, 2019).
leukemia (11 papers, 2012 to 2024). A malignant (clonal) hematologic disorder, involving hematopoietic stem cells and characterized by the presence of primitive or atypical myeloid or lymphoid cells in the bone marrow and the blood. "To determine the impact of SKP2 on leukemogenesis, we have used a Notch-induced murine leukemia model driven by the ICN allele, which models the rare t(7:9) translocation and is a potent transcriptional transactivator." (PMID 31772299, 2020). "However, dysregulation of SKP2 has been implicated in various cancers, including leukemia, and is also associated with drug resistance." (PMID 38559562, 2024). "Overexpression of Skp2 in leukemia cells can contribute to drug resistance through several mechanisms." (PMID 38559562, 2024). "miR-203 targets SKP2 and regulates cell cycle and self-renewal in the hematopoietic stem cells and leukemia cells." (PMID 38559562, 2024). "Small molecules targeting SKP2 activity or SKP2 complex assembly have been examined in leukemia cells and in xenograft tumor models, respectively, and have been proven to be effective as anticancer agents." (PMID 33628597, 2021). "It is possible that during this window, in the context of SKP2 absence, some incipient leukemia cells were able to access SKP2-independent mechanisms to fully transform into T-ALL." (PMID 31772299, 2020). "Although the role of histone methyltransferase MLL in PCa is unclear, it was reported that leukemogenic MLL fusions were resistant to SKP2-mediated degradation, suggesting the involvement of SKP2 in epigenetic modification mechanisms of histone in Leukemia." (PMID 25596733, 2015). "In contrast, all Skp2−/− ICNns recipients developed leukemia and showed PB, BM, and tissue involvement similar to that observed in recipients of Skp2+/+ ICN cells; however, they exhibited a delayed onset of disease and slower kinetics of progression, which persisted in secondary transplants." (PMID 31772299, 2020). "In addition, the E3 ligase family members Fbxl2, Fbxl10, and SKP2 participate in the proliferation of leukemia cells by regulating the ubiquitination pathway." (PMID 29555946, 2018). "The E3 ligases Fbxl2, Fbxl10, and SKP2 participate in the proliferation of leukemia cells." (PMID 29555946, 2018). "It is noteworthy that in this model of aggressive T-ALL, SKP2 deletion prevented leukemia development in ~30% of mice, which were disease-free for the entire period of the follow-up (>1 year), and delayed onset of leukemia in two thirds of the transplanted cohort." (PMID 31772299, 2020). "Notably, depletion of Skp2 enhances sensitivity of leukemia cells to chemotherapy agents, which indicates that Skp2 might be a target for leukemia stem cell treatment." (PMID 30999935, 2019). "MLL fusion proteins are resistant to ubiquitin‐proteasome‐mediated degradation due to the diminished interactions with E3 ligases Skp2 and Cdc20,37 leading to the stabilization and onset for MLL‐rearranged leukaemia." (PMID 33599085, 2021). "Targeted inhibition of SKP2 by genetic deletion or pharmacological blockade markedly inhibited proliferation of human T-ALL cells in vitro and antagonized disease in vivo in murine and xenograft leukemia models, with little effect on normal tissues." (PMID 31772299, 2020). "Overall, these data demonstrate that absence of SKP2 can prevent leukemia development by driving exhaustion of Skp2−/− ICN population in some recipients." (PMID 31772299, 2020). "Since Skp2 protein expression is also increased in AML, we analyzed a potential additional role of Skp2 in Cdh1 degradation and found elevated Cdh1 levels in leukemia cells depleted of Skp2." (PMID 27374082, 2016).
bladder cancer (9 papers, 2013 to 2026). "A similar effect was observed in bladder cancer, where mir-1236-5p stopped the cell cycle in S phase by influencing F-box protein S-phase kinase-associate protein 2 (Skp2) expression." (PMID 33123872, 2021). "Previous results have indicated that SKP2 expression was associated with higher tumor grade in BCs or bladder cancers." (PMID 30341246, 2019). "The results indicated that SKP2 mRNA levels in bladder normal tissues were decreased as compared with bladder cancer tissues." (PMID 36293387, 2022). "The IHC results also showed that HUR expression was decreased and SKP2 expression was elevated in N-butyl-N-(4-hydroxybutyl) nitrosamine (BBN)-induced mouse bladder cancers." (PMID 36293387, 2022). "(−)-gochnatiolide B inhibited Skp2 in bladder cancer by attenuating cell proliferation." (PMID 32165861, 2020). "It functions as an inhibitor of the Wnt signaling pathway, and could regulate SKP2 and c-Myc expression, resulting in G1 arrest and the inhibition of proliferation in urinary bladder cancer cells." (PMID 29875348, 2018). "Wnt signaling also requires the regulation of SKP2, which is the F-box subunit of the ubiquitinligase complex SCFSKP2/p27 degradation pathway, for Wnt signaling-mediated G1-S transition in human urinary bladder cancer cells." (PMID 24098916, 2013).
neuroblastoma (9 papers, 2006 to 2023). Neuroblastoma (NB) is the most common solid, extracranial childhood tumor. "In this study, we have repurposed the anti-psychotic drug Prozac to disrupt CKS1/SKP2/p27Kip1 signalling and assess its potential as an anti-neuroblastoma agent in vitro and in vivo." (PMID 31900399, 2020). "High expression of the Skp2 component of the SCFSkp2 ligase was included in the genetic signature of aggressive stages of neuroblastoma." (PMID 25594028, 2014). "In neuroblastoma tumors, SKP2 expression has been shown to tightly correlate with E2F1 expression, and both genes are expressed at significantly higher levels in MYCN amplified tumors." (PMID 23226679, 2012). "Previously, SKP2 was determined as a prognostic factor of high risk neuroblastoma independent of MYCN status." (PMID 35764946, 2022). "Whether or not SKP2 is a direct target gene of MYCN, the prognostic significance of SKP2 overexpression in neuroblastoma has been demonstrated in primary tumor samples." (PMID 23226679, 2012). "Taken together, SKP2 has prognostic significance in neuroblastoma and could be a promising novel therapeutic target, however further studies investigating the role of SKP2 in neuroblastoma are required." (PMID 23226679, 2012). "The exact role of SKP2 in neuroblastoma pathogenesis is currently unclear." (PMID 23226679, 2012). "Consequently, together with in vitro experiments, crossing SKP2 knockout mice with murine models of neuroblastoma, such as the transgenic TH-MYCN mouse, the role of SKP2 in driving neuroblastoma could be elucidated." (PMID 23226679, 2012). "Of interest, although not directly linked to SKP2, bortezomib is shown to induce apoptosis and inhibit cell growth, migration, angiogenesis, and metastasis both in vitro and in murine models of chemosensitive and chemoresistant neuroblastoma." (PMID 23226679, 2012). "These included SKP2 or MYCN, confirming prior data, and ID2, which drives oncogenesis in other RB1null and RB1wt/MYCNamp contexts, including neuroblastoma." (PMID 32572160, 2020). "Neuroblastoma tumours have been shown to express high levels of SKP29 and c-MYC upregulates SKP2 expression." (PMID 31900399, 2020). "Summary of studies which have shown increased SKP2 expression in the presence of MYCN and/or MYCN amplification in neuroblastoma." (PMID 23226679, 2012). "It has been suggested that deregulated MYCN expression in MYCN amplified neuroblastoma indirectly upregulates SKP2 via the induction of CDK4, thereby reducing the abundance of repressive pRB-E2F1 complexes bound to the SKP2 promoter and providing an entry point into the SKP2 autoinduction loop." (PMID 23226679, 2012).